Y_RNA (Y RNA )
Gene: Miscellaneous RNA gene on chromosome 7 (69,507,510 to 69,507,622, reverse strand). Ensembl gene ENSG00000200857.
Homologues: Orthologues: chimpanzee Y_RNA (100% identical), macaque Y_RNA (94% identical). Paralogues in human: Y_RNA (82% identical), RNY1 (81% identical), RNY1P11 (81% identical), Y_RNA (81% identical), RNY1P8 (80% identical), Y_RNA (80% identical), Y_RNA (79% identical), RNY1P12 (78% identical), Y_RNA (78% identical), RNY1P16 (77% identical), RNY1P3 (77% identical), Y_RNA (77% identical), and 91 more.